MITF (melanocyte inducing transcription factor)
Diseases named in the same sentence as MITF in open-access papers (continued):
Sharing a sentence is not in itself a finding about the gene and the disease.
tumor (372 papers, 2008 to 2026). "Recently, we have identified the microphthalmia-associated transcription factor (MITF) as a critical player in pro-survival signaling and tumor growth." (PMID 40343114, 2025). "As KIT-containing EVs have been implicated in GIST invasion, these findings suggest that MITF contributes to tumor progression through coordinated regulation of autophagy and EV-mediated signaling." (PMID 41168571, 2025). "Our analysis reveals a statistically significant association between conventional BRISK categories and MITF protein expression in tumor cells (Kruskal–Wallis ANOVA test, P ═ 0.027)." (PMID 39976551, 2025). "We next examined the functional consequences of MITF loss on mTOR inhibition-induced autophagy and on extracellular vesicle (EV) content and secretion, given their known interplay in tumor progression." (PMID 41168571, 2025). "Re‐pigmentation of amelanotic tumours can occur due to gene expression changes such as mutations in the MITF gene or changes in the tumour microenvironment." (PMID 40898695, 2025). "A recent study used mouse models to demonstrate that MITF is upregulated in tumor-associated monocytic MDSCs and contributes to their immunosuppressive function." (PMID 40894019, 2025). "We identified genes, such as SPP1, preferentially expressed in tumor-associated macrophages (TAMs) and noted the MITF regulatory network appeared active in the M2-like TAMs." (PMID 40894019, 2025). "To investigate the effect of treatments on melanocytic differentiation, we evaluated the expression of microphthalmia-associated transcription factor (MITF) in tumor tissues of intraperitoneal groups by immunofluorescence analysis." (PMID 40806647, 2025). "The interplay of these factors contributes to the intricate SOX10‐mediated MITF regulation underlying tumor heterogeneity." (PMID 40458894, 2025). "For instance, tumor subpopulations can be stratified based on the expression of microphthalmia-associated transcription factor (MITF), with MITF-high and MITF-low states contributing to both intra- and intertumoral heterogeneity." (PMID 40574832, 2025). "Recent evidence suggests that MITF is expressed predominantly in tumor-associated myeloid-derived suppressor cells (MDSCs) to regulate their differentiation and immunosuppressive functions." (PMID 38351314, 2024). "Regarding the genetic background, this tumor is associated with the alteration of MITF gene, which is fused either with the ACTB or ACTG1 gene." (PMID 39264472, 2024). "In xenografts, both c-MET (encoded by MET) and tyrosine kinase inhibition suppressed tumor growth by inhibiting MITF." (PMID 38916046, 2024). "Its expression anticorrelates with MITF, and its upregulation and overexpression in the Epgn3 high-risk/invasive cellular state are suppressive for invasiveness, tumor growth, and metastatic potential." (PMID 38319712, 2024). "The prediction of MITF activation is significant given that recently published data demonstrated that MITF expression was associated with aggressive tumor behavior and increased the migratory and invasive capabilities of ccRCC cells." (PMID 37189628, 2023). "Early research revealed that inhibition of BRN2 expression results in complete loss of tumour formation in mice, and the loss of melanocyte markers including MITF." (PMID 37181747, 2023). "Transcription factors (TFs) associated with tumor metastasis and progression, such as MITF, MYC, and CTNNB1, showed high transcription activity in the MYC+MEL subcluster." (PMID 38065972, 2023). "We confirmed that the sensitivity of the tumor cells to T cells was strongly associated with their ability to downregulate MITF." (PMID 36812891, 2023). "Contrarily, ACY-1215 treatment of MUM cells significantly downregulated MITF and MITF signaling pathway associated protein(s) expression levels, which probably contributed to the observed anti-tumor effects." (PMID 36012642, 2022).
tumor (continued). "In summary, MITF expression was associated with aggressive tumor behavior, and increased the migratory and invasive capabilities of ccRCC cells." (PMID 34208068, 2021). "Collectively, high MITF expression was associated with shorter progression-free survival in patients with OvCa, indicating that elevation of MITF in tumor cells is linked to metastatic progression of OvCa." (PMID 33371469, 2020). "They confirmed prominent SNAIL2 and ZEB2 expression in normal melanocytes, and postulated that both act as tumor-suppressor proteins by activating an MITF-dependent (MITF = Microphthalmia-associated transcription factor) melanocyte differentiation program." (PMID 28671620, 2017). "This was reflected in PAX3, MITF, as well as MITF target gene expression, demonstrating that reduced MITF function is linked to repressed tumor growth." (PMID 26977879, 2016). "First, PEComa was considered as a differential diagnosis, because the tumor cells were partially positive for MiTF and they were associated with an abnormal vessel." (PMID 27998309, 2016). "POU3F2 has been shown to be responsive to MAPK pathway activation and to modulate the levels of microphthalmia-associated transcription factor (MITF) so as to suppress the differentiated melanocytic phenotype and to enhance tumor metastasis." (PMID 25395235, 2015). "These included mutations in MEK1, MEK2 and in MITF; and in three cases multiple resistance conferring mutations within same tumor were observed." (PMID 24743024, 2014). "Based on the histologic and molecular features of melanotic Xp11 TRCs, Argani and colleagues considered these tumors unique members of the microphthalmia-associated transcription factor (MiTF)/Transcription Factor Enhancer (TFE) family of neoplasms." (PMID 24735727, 2014). "miR-137 is a tumor suppressor and a regulator of the transcription factor microphthalmia-associated transcription factor (MITF) in uveal melanocytes." (PMID 24179439, 2013). "This analysis revealed a loss of the immune-related molecule CCL2 over time, contributing to a “cold” tumor microenvironment, and an increase in metastasis-associated molecules like MITF, KIT, and VIM, suggesting a potential transition to a mesenchymal phenotype." (PMID 38975339, 2024). "We identified UM-associated hybrid cells based on co-expression of melanocytic tumor proteins: Microphthalmia-associated transcription factor (MITF), Tyrosinase (TYR), Melan-A (MLANA), premelanosome protein (PMEL, GP100), 5-hydroxytryptamine receptor 2B (HTR2B) and the pan-leukocyte marker CD45." (PMID 38106024, 2023). "Changes in the tumour microenvironment, such as hypoxia or nutrient starvation, may also cause a decrease in MITF expression and greater invasiveness." (PMID 35682684, 2022). "The further integrative analytics of transcriptomic and clinical data has shown a tumor-suppressive activity of a microphthalmia-associated transcription factor (MITF), which directly affects the heat shock protein crystallin alpha B that is downregulated in PCa." (PMID 33525365, 2021). "MITF was significantly associated with tumor progression in ccRCC, both in vitro and in vivo." (PMID 34208068, 2021).
tumor (continued). "Oncogenic BRAF, through decreased MITF expression and enhanced IL-1α and IL-1β secretion, triggers PD-L1 and PD-L2 expression in tumor-associated fibroblasts which also contributes to suppression of tumor-infiltrating T cell function." (PMID 33276788, 2020). "Analysis of changes in MITF expression using a publicly available microarray data set (Gene Expression Omnibus (GEO)) revealed that the majority of relapsed tumours showed altered expression of MITF, and the extent of MITF increase or loss was very diverse, similarly as in our study." (PMID 31354817, 2019). "Microphthalmia‐associated transcription factor (MITF) is a melanocyte‐specific transcription factor that binds to the promoter site of multiple target genes involved in melanocyte cell development, pigmentation and neoplasia." (PMID 30511391, 2019). "Tumor tissue-based driver mutations in genes like BRAF or MITF might be of high impact for the treatment outcome of targeted therapies, but do not correlate with chemotherapy outcome." (PMID 26799424, 2016). "In contrast, EPHA3 and MITF are under-expressed in cancers or have been shown to act as tumor suppressors; the somatic mutations may create new target sites that lead to increased inhibition of translation or degradation of the mRNAs." (PMID 23091610, 2012). "Additionally, corin treatment with or without PLX4032 led to increased expression of H3K4Me2, H3K27Ac, DUSP1, and DUSP5, as well as increased expression of markers of apoptosis and tumor hypoxia in BRAFi-R tumors, with associated decreases in the expression of both MITF and AXL." (PMID 38300709, 2024). "Conversely, in CMM cells TGFB has a different role as it appears involved in the tumor aggressiveness, angiogenesis, cells growth, migration and regulation of immunological surveillance: most of these mechanisms seem to be also associated to PAX3d and MITF expression." (PMID 29156734, 2017). "Moreover, this can create a situation of enhanced tolerance during BRAF and MEK inhibitor therapy, because the number of tumour‐associated macrophages increases in response to the inhibitors, and this correlates with increased expression of MITF during treatment." (PMID 25818589, 2015). "The observed lack of a statistically significant relationship between CD8+ lymphocytes and MITF expression underscores the complexity of immune–tumor interactions." (PMID 39976551, 2025). "Together, our findings implicate MITF as a regulator of autophagy and EV-mediated communication in GISTs, highlighting the MITF–autophagy–EV axis as a promising therapeutic target to limit tumor growth and overcome drug resistance." (PMID 41168571, 2025). "This study highlights MITF as a promising target for therapeutic intervention in GISTs owing to its regulatory influence on key pathways involved in tumor growth, autophagy, and metastasis." (PMID 41168571, 2025). "When the signal is turned on, a delayed MITF response maintains the malignant state of the tumor, potentially promoting tumor progression." (PMID 40458894, 2025). "Furthermore, miR-137 could act as a tumor suppressor by inhibiting the Wnt/β-catenin signaling pathway and suppressing cell proliferation, given that it causes the downregulation of MITF and the destabilization and inhibition of nuclear translocation of β-catenin." (PMID 40362297, 2025). "MITF expression that increases in TAM-MGs with tumor grade, also is increased in fetal compared to postanal microglia." (PMID 38895459, 2025). "The knockdown of MITF also reduced the impact of METTL10 on tumor progression in xenografts derived from MKN45 cells." (PMID 41114928, 2025). "Taken together, these findings suggest that the proliferation and tumor progression driven by METTL10 in GC are dependent on MITF‐mediated regulation of purine metabolism." (PMID 41114928, 2025).
tumor (continued). "Co-amplified with MITF and transcriptionally linked to the melanocytic lineage programme, SAMMSON sustains the bioenergetic and biosynthetic capacity of tumour cells by directly coordinating mitochondrial translation and integrity." (PMID 41463281, 2025). "Confirming the snRNA-Seq results, MITF and BRAF showed higher expression levels in the ROIs located in tumour tissues, with MITF showing a bigger difference." (PMID 41168392, 2025). "This mRNA-based CNV profile of the primary tumour closely resembled that obtained from DNA methylation data, including the presence of amplification of the chromosome bands encompassing MITF and BRAF." (PMID 41168392, 2025). "While the precise contribution of these metabolic changes to accelerated tumor growth remains to be fully elucidated, a shift in the MITF/MYC balance provides additional insight." (PMID 40558540, 2025). "MITF expression was assessed in six tumor tissues for each engraftment, showing a reduction after ML329 treatment." (PMID 40343114, 2025). "While CD8+ T cells are well known for their cytotoxic role in anti-tumor immunity, our findings suggest that additional factors within the tumor microenvironment influence MITF expression." (PMID 39976551, 2025). "While most tumor meta-programs exhibited melanocytic differentiation (high MITF and CTNNB1), two meta-programs-Respiration and Stress-expressed dedifferentiation markers including AXL, SOX9, EGFR and NGFR." (PMID 40890106, 2025). "This is reminiscent of the ABCB5 gene, where its expression seems to mark slow-cycling, MITF-high tumor-initiating cells with a more differentiated phenotype." (PMID 40528051, 2025). "Microenvironmental factors, such as hypoxia, nutrient availability, and cytokines further modulate MITF levels, impacting tumor behavior and response to targeted therapies and immune checkpoint inhibitors." (PMID 39976551, 2025). "Proteomic changes include reduced KIT levels in both cells and EVs, suggesting that MITF regulates EV cargo to influence tumor signaling and invasion." (PMID 41168571, 2025). "MITF, Ki67, BRAF, and PD-L1 are associated with prognosis factors, like the Breslow thickness, tumour ulceration, type of inflammatory infiltrate, and response to treatment." (PMID 40507250, 2025). "As illustrated in the MM10 tumor, which bore the presence of a well-defined ZEB1high clone, increased ZEB1 expression was not only associated with low ZEB2 and MITF expression, but also with decreased SOX10 levels." (PMID 38519642, 2024). "In total, 13 of 97 patients (13%) carried a germline (likely) pathogenic variant in a well-known tumor predisposition gene: APC (n = 1), BRCA2 (n = 2), CHEK2 (n = 4), DICER1 (n = 4), HOXB13 (n = 1), and MITF (n = 1)." (PMID 38415346, 2024). "Previously, AXL+ tumor cells were identified to be highly resistant to targeted therapy, whereas more differentiated MITF+ tumor cells do respond to RAF and MEK inhibitors." (PMID 39697983, 2024). "Single-cell profiling of both malignant and stromal cells derived from tumours of 19 individuals has confirmed that MITF is a key biomarker for distinct phenotypic states." (PMID 39092608, 2024). "Precise monitoring of intra-tumor heterogeneity during phenotype transitions over time was achieved by flow cytometry using stable cell lines established with a MITF promoter-GFP reporter construct and combined with NGFR membrane staining." (PMID 38519642, 2024). "Invasive MITF− cells require a longer period to initiate in vivo growing tumor by comparison with MITF+ proliferative cells." (PMID 38191367, 2024). "Mice injected with either TPC2 KO or Rab7a KO B16F10-luc cells exhibited significantly decreased tumor weights and reduced dissemination as well as reduced MITF and β-Catenin staining in ex vivo tumor tissue compared to mice injected with WT B16F10-luc cells." (PMID 39562548, 2024).
tumor (continued). "In total, 13 patients (13%) carried a P/LP variant in a known autosomal dominant tumor predisposition gene: APC (n = 1), BRCA2 (n = 2), CHEK2 (n = 4), DICER1 (n = 4), HOXB13 (n = 1), and MITF (n = 1)." (PMID 38415346, 2024). "The MAPK cascade leads to activation of ERK1 and ERK2 which translocate into the nucleus to regulate MiTF, cMYC and other transcription factors to sustain cell cycle progression, tumor invasion, metastasis and immune evasion." (PMID 37608347, 2023). "The high GREB1 and MITF expression levels were significantly correlated with pathological T factor (pT), which reflects the tumor thickness." (PMID 37658191, 2023). "The impact of TFEB knockdown and its family members TFE3 and MITF on PDAC tumor growth has been evaluated in subcutaneous xenografts, but not in orthotopic models, that better recapitulate human disease." (PMID 36746928, 2023). "IDO1-inhibiton even protected tumour cells from switching off protein translation and Melanocyte Inducing Transcription Factor (MITF) production by IFN-γ." (PMID 37503572, 2023). "Mechanistically, LN metastasis required tumor cells to undergo a metabolic shift towards fatty acid metabolism induced by the key transcription factor MITF in MYC+MEL cells." (PMID 38065972, 2023). "This was followed by tumor cell dedifferentiation and a dormant phenotype marked with decrease in MITF expression." (PMID 36906600, 2023). "We analyzed the expression profiles of MITF and Ki67 in A375P‐xenografts, in which dense tumor masses were surrounded by streams of migrating cells." (PMID 36692026, 2023). "This kind of analysis also validated the behaviour of the MITF gene signature with increased enrichment in MEL-like tumours." (PMID 36765773, 2023). "Such dataset outcomes illustrate for the first time that the anti-tumour effect of miR-585-5p in GC is due to direct simultaneous inhibition of MITF, CREB1 and MAPK1 expression." (PMID 36268034, 2022). "This interaction network shows that miR-585-5p directly or indirectly regulates MITF expression and activity by simultaneously repressing target molecules, accounting for the anti-tumour role of miR-585-5p in inhibiting GC growth and metastasis." (PMID 36268034, 2022). "This so‐called phenotype switching is regulated by transcription factors like MITF as a prominent member, controlling tumor growth, cell division and cell differentiation." (PMID 34951143, 2022). "In our study, decreased MITF and OPN4 (also higher BMAL1) gene expression is associated with a slower proliferation, higher antitumorigenic TME, and therefore, reduced tumor growth." (PMID 35562405, 2022). "Comparably, in UM, MITF seems to have an intricate role balancing between UM tumor growth and tumor suppression activities." (PMID 36012642, 2022). "Ultimately, pharmacological inhibition of β-catenin or MITF increased the efficacy of anti-PD-1 immunotherapy in preclinical xenograft tumor model by promoting ferroptosis." (PMID 36429010, 2022). "In previous work, we showed that silencing of SH3BP2 diminished KIT, PDGFRA, and MITF levels lead to a reduction in tumor growth in vitro and in vivo." (PMID 36551682, 2022). "Overall, this investigation not only revealed the tumour-inhibiting role of miR-585-5p in GC proliferative/metastatic properties but also defined the mechanism of miR-585-5p downstream signalling through MITF regulation in multiple aspects of gene expression." (PMID 36268034, 2022). "Turning off MITF activity results in tumour regression with remaining persister cells at the MRD site." (PMID 35929478, 2022). "In contrast, MITF has been shown to increase p16 expression in UM, where CDKN2A mutations have rarely been described, supporting the idea that MITF can induce cell cycle arrest and behave as a tumour suppressor gene." (PMID 35682684, 2022).